HIPK3 (homeodomain interacting protein kinase 3)
Diseases named in the same sentence as HIPK3 in open-access papers (continued):
Sharing a sentence is not in itself a finding about the gene and the disease.
tumor (continued). "The in vivo results parallel the in vitro results and show that KLF12 and HIPK3 overexpression stimulate tumor growth and chemoresistance, respectively." (PMID 25344865, 2014). "Overexpression of KLF12 and HIPK3 significantly stimulated tumor growth and chemoresistance in miR-382-overexpressing MNNG/HOS cell xenograft models, respectively." (PMID 25344865, 2014). "We examined whether there was a significant correlation between the HIPK3 expression H-score and clinicopathologic characteristics (gender, age, lymph-node invasion, tumor stage, histological grading, and survival time in days)." (PMID 38105269, 2023). "In vitro cell results also confirmed that HIPK3 over-expression could inhibit tumor growth and malignant characteristics." (PMID 33495417, 2021). "The results of these experiments suggest that the HIPK3 may exhibit tumor suppressor role in CCA." (PMID 38105269, 2023). "HIPK3 appears to act as a tumor suppressor and could be a direct target of miR-205-5p." (PMID 38105269, 2023). "Intriguingly, circ-HIPK3 plays the opposite role in tumor occurrence and progression in other tumors, which strongly suggests that whether a single circRNA acts as an oncogene or a tumor suppressor gene depends on tumor types and which miRNA it sponges." (PMID 34956899, 2021). "And HIPK3 may exert its tumor suppressive potential through phosphorylation of FADD." (PMID 35096570, 2021). "In contrast, circ-HIPK3 and circ-PPP1R12A are significantly upregulated in CRC and function as oncogenes through the promotion of tumor cell proliferation and metastasis." (PMID 34660182, 2021). "We transplanted HIPK3-overexpressing and NC HCT116 cells into nude mice for subcutaneous tumor formation." (PMID 35096570, 2021). "This indicates that the patient had a tumor specific homozygous WT1 deletion and a heterozygous deletion extending at least to the HIPK3 gene." (PMID 27213811, 2016). "As HIPK3 had a significantly different expression between tumor tissues and non-cancerous normal tissues, then we used ROC curves to analyze the diagnostic efficiency of HIPK3." (PMID 33495417, 2021). "HIPK1 and HIPK3 had a lower expression in tumor tissues than that in corresponding non-cancerous normal tissues." (PMID 33495417, 2021). "To determine whether the anti-tumor effects of miR-382 on these OS cells could be partly explained by its targeting of KLF12 and HIPK3, we first analyzed how KLF12 and HIPK3 overexpression affected in vitro and in vivo cell growth and chemosensitivity." (PMID 25344865, 2014). "The results show that low expression of HIPK3 could be a predictor of poor overall survival (OS) and disease-free survival (DFS) with univariate and multivariate analysis in ccRCC, and can be used as a tumor suppressor gene among 4 HIPKs." (PMID 33495417, 2021).
cardiovascular disease (2 papers, 2022 to 2023). "CircRNAs generated from human HIPK3 (circ-HIPK3) have been shown to play important roles in cardiovascular disease." (PMID 36800233, 2023). "CircRNAs derived from HIPK3 have been discovered to play an important role in cardiovascular diseases." (PMID 36800233, 2023).
metabolic disorder (1 paper, 2022). "Circular RNA HIPK3 (circRNA HIPK3) is a highly conserved non-coding RNA that mediated the vascular dysfunction and metabolic disorder induced by DM." (PMID 35870977, 2022).
HIPK3 also shares sentences with these, for which no sentence is quoted: acute kidney injury (2 papers); dermatitis (2); glioblastoma (2); osteoarthritis (2); acute myocardial infarction (1); allergic conjunctivitis (1); angina (1); Aphasia (1); asthma (1); atherosclerosis (1); Autoimmunity (1); candidiasis (1); cholangiocarcinoma (1); diabetic retinopathy (1); epilepsy (1); esophageal cancer (1); gout (1); infection (1); Insulin resistance (1); ischemic heart disease (1); liver cirrhosis (1); malignant glioma (1); melanoma (1); nasopharyngeal carcinoma (1); neuropathy (1); Obesity (1); prostate (1); rhabdomyosarcoma (1); Stroke (1); thyroid cancer (1).